ERBB2 (erb-b2 receptor tyrosine kinase 2)
Diseases named in the same sentence as ERBB2 in open-access papers (continued):
Sharing a sentence is not in itself a finding about the gene and the disease.
bladder cancer (continued). "In this study, we investigated the effects of the aqueous extract of Cinnamon on human bladder carcinoma cell line 5637, especially on the gene expression of HSF1, ErbB2, and LDHA and the level of LDHA and HSF1 proteins and apoptosis." (PMID 35990198, 2022). "The bladder cancer category included proteins such as MAPK1 (P28482), EGFR (E9PFD7), SRC (P12931), and ERBB2 (B4DTR1)." (PMID 36362028, 2022). "A subset of primary bladder cancers demonstrate somatic alterations and/or protein overexpression of ERBB2 (HER2)." (PMID 33420073, 2021). "We have demonstrated that ctDNA profiling can identify previously proposed biomarkers for therapy response in bladder cancer, including alterations in FGFR3, ERCC2, and ERBB2, and TMB." (PMID 33420073, 2021). "This pathway is activated in around 40% bladder cancer cases (FGFR3: > 10%, EGFR:> 10%, ERBB2:~ 10%, ERBB3:~ 10%, NRAS/HRAS/KRAS:~ 10%, PTEN: ~ 10%, AKT3:~ 10%)." (PMID 31665050, 2019). "Genes co-amplified with ERBB2 (GRB7, MIEN1, PGAP3, and STARD3) exhibited the highest amplification frequency in esophageal cancer, followed by stomach, breast, uterine, and bladder cancer." (PMID 29190909, 2017). "For instance, we have demonstrated activation of ERBB2 and ELK1, both of which have also been shown to induce CDDP resistance, by androgens in AR-positive bladder cancer cells." (PMID 27322140, 2016). "Other genes, such as the ERBB2/HER2 and PTEN, have been reported to be involved in the progression of advanced bladder cancer." (PMID 26924873, 2016). "Recently, it has been reported that ErbB2 and EMP3 reciprocally up-regulate each other accompanied with activation of PI3K/Akt pathway to promote proliferation and migration of human bladder cancer cells." (PMID 26472188, 2015). "The growth factor receptors including ERBB2, ERBB3 and EGFR have been found to be altered or amplified in bladder cancer and have the potential to activate PI3K/AKT signaling pathway." (PMID 26597249, 2015). "In KEGG bladder cancer pathway, the oncogenes NRAS and ERBB2 were found up-regulated, hypothetically, due to lower of expression of miR-28-5p and miR-125b, respectively." (PMID 23717626, 2013). "Regarding growth factor receptor genes, treatment with DOX increased some of these genes, such as ErbB2, ErbB4 and FGF2 in the tumors, which are up-regulated in bladder cancers and responsible for disease progression." (PMID 22824624, 2012). "In contrast, several coexpression patterns were independent prognostic indicators of bladder cancer death, namely, EGFR-ErbB2, ErbB2-ErbB3, and high EGFR or ErbB2 plus low ErbB3 or ErbB4." (PMID 22991510, 2012). "In bladder cancer, EGFR/ERBB2 is frequently overexpressed, which correlates with higher tumor grade/stage and poorer prognosis." (PMID 22922989, 2012). "Our study found that ERBB2, the target of RC48, is highly enriched in luminal bladder cancer." (PMID 39840049, 2024). "Moreover, in 413 bladder cancer samples (data derived from TCGA), a significantly higher expression level of four genes, RAD21, RAD51, BARD1, and ERBB2, was observed in ERBB-low as compared to ERBB-high tumours." (PMID 39080120, 2024). "Molecular subtypes of HER2/ERBB2 negative and positive with distinct clinical outcomes have been identified in recent years; however, it is still under investigation for bladder cancer." (PMID 37474724, 2023). "Similarly, abnormal amplifications of the ERBB2, mdm2 and FGFR3 genes were found at a high frequency in bladder cancer." (PMID 38067407, 2023). "The mutations also appear more random, lacking a prominent mutated gene like ERBB2 in pulmonary cancer and BRAF in bladder cancer." (PMID 37414794, 2023). "In AR-positive bladder cancer cells, DHT could activate the epidermal growth factor receptor (EGFR)/ERBB2/ERK pathway in the presence of the epidermal growth factor (EGF)." (PMID 33919565, 2021).
bladder cancer (continued). "Namely, HER2 (also known as ErbB2 or HER2/neu) is an heavily glycoprotein, member of the EGF receptor (EGFR) family, that is overexpressed in several malignancies, including advanced stage bladder cancer." (PMID 29207682, 2017). "CCND1 amplified bladder cancers may be sensitive to CDK4 inhibitors; ERBB2 amplified tumors may be sensitive to lapatinib, trastuzumab, or T-DM1; and MDM2 inhibitors are in current clinical development." (PMID 23593348, 2013). "However, gene amplification alone does not solely drive high HER2 expression in bladder cancer; SNVs occur prior to ERBB2 amplification." (PMID 38455962, 2024). "HER2-negative IHC staining demonstrated a high predictive value and specificity for negative ERBB2 gene amplification, suggesting that it is a reasonable screening test for HER2 status in bladder cancer." (PMID 25720673, 2015). "In addition, in multiple bladder cancer datasets (including TCGA-BLCA, GSE13507, GSE48075, and GSE32894), we observed a negative correlation between STAT3 and ERBB2 in mRNA levels." (PMID 39840049, 2024).
colon carcinoma (275 papers, 2003 to 2026). "Rates of concurrent ERBB2 mutation were slightly higher in HER2-amplified colon cancer (16.4%, 10/61) than in HER2-amplified rectal cancer (15.4%, 4/26)." (PMID 40742050, 2025). "ErbB2 and ErbB3 are tyrosine kinase receptors that have been linked to the growth of human colon cancer and are highly expressed in HT-29 cells." (PMID 35971151, 2022). "This is in contrast to the reported death of a patient with colon cancer metastatic to lung and liver after ERBB2-CAR therapy caused by tonic signaling through a Herceptin-based third-generation CAR." (PMID 33809981, 2021). "Similarly, the identification of aberrant signalling downstream of (Epidermal growth factor receptor) EGFR mutation and (Receptor tyrosine-protein kinase erbB-2) Her2 amplification opened new therapeutic windows in lung, breast and colon cancer." (PMID 37569364, 2023). "In addition, recent clinical investigations demonstrated an association between ERBB2 overexpression and tumour-associated proteolysis in gastric and colon cancer, suggesting a direct role for ERBB2 in invasion and metastasis through upregulation of proteolytic enzymes." (PMID 15054465, 2004). "Several days later, next-generation sequencing (NGS) of biopsy tissue from colon cancer showed ERBB2 gene amplification, accompanied by an exon 20 insertion mutation [variant allele frequency (VAF) 46.51%]." (PMID 39790478, 2025). "We similarly plotted count densities of the four highest ranking cCREs outside of Chr17q12–21, but tumor peaks in these regions were at least an order-of-magnitude lower than the ERBB2 peaks in the breast and colon tumor samples." (PMID 39946483, 2025). "For colon cancer, liquid biopsies were able to detect ERBB2 alterations in circulating tumor DNA (ctDNA) that were confirmed in tissue samples, suggesting that HER2 has potential as a plasma biomarker." (PMID 39199625, 2024). "A recent study showed cetuximab-resistant CRC tumors to have mutational hotspots located in the genomic landscapes of receptor tyrosine kinases (EGFR-ERBB2), RAS, and WNT pathways, and ERBB2 (HER2 gene) amplifications are observed in colon cancer." (PMID 35664781, 2022). "After several chemotherapy regimens, 1 × 1010 CAR-T cells targeting ERBB2, which has been found to be overexpressed in several different cancers including colon cancer, were used as the fourth line of treatment." (PMID 35274719, 2022). "ERBB2 encodes the human epidermal growth factor receptor 2 (HER2), which is overexpressed, amplified, or both in several human malignancies including breast, ovarian, and colon cancers." (PMID 34842634, 2021). "The oncogene ERBB2 has been shown to be amplified or overexpressed in multiple cancers, including colon cancers." (PMID 33959500, 2021). "The PDX 36M1 was derived from a synchronous liver metastasis of a stage IV colon tumor, and the PDX 40 from a stage IV colon tumor, which presented two activating mutations in PIK3CA and ERBB2 genes." (PMID 31627299, 2019). "In 2010, death of a patient with colon cancer metastasis to the lung and liver following ERBB2-targeting CAR-T cell therapy was reported." (PMID 31754328, 2019). "The use of PDX with different mutational profiles shows the efficacy of the combination on a colon tumor liver metastasis (PDX 36M1) and on a primary tumor mutated for PIK3CA and ERBB2 genes (PDX 40)." (PMID 31627299, 2019). "These markers are also positive in other cancers such as prostate adenocarcinoma (Her2/erbB2, CK7 and GCDFP15) and colon cancer (Her2/erbB2 and CEA)." (PMID 30458743, 2018). "In another study, hypoxia was found to regulate cellular behavior in colon cancer by modulating the ErbB2/ErbB3 signaling pathway synergistically with the upregulation of miR-214, although in an miRNA-independent manner." (PMID 27381447, 2016).
colon carcinoma (continued). "Other investigators also have shown that heregulin is co-expressed with ErbB2 expression in colon cancer specimens and that autocrine activation of ErbB2 occurs through dimerization to ErbB3 in a colon carcinoma cell line." (PMID 25416285, 2014). "It was demonstrated that CUR is able to inhibit EGFR and ErbB2 phosphorylation in breast and colon cancer cell lines and that the combined treatment of RES+CUR increases these effects in colon carcinoma cell lines." (PMID 25296980, 2014). "Of note, the primary colon cancer tissue (ID#2208843) had ERBB2 V842l mutation and PDX model had the same ERBB2 V842I mutation." (PMID 25526474, 2014). "Heregulin (HRG) is co-expressed with ErbB2 proteins in human cancer cells, and heterodimerization with ErbB3 activates ErbB2 through an autocrine mechanism in colon cancer cells." (PMID 23739740, 2013). "Further, the ability of SMC/Muc4 to alter ErbB2 localization in polarized human colon carcinoma CACO-2 cells has been demonstrated, indicating a strong physical association between the two molecules." (PMID 16551361, 2006). "Fragments of the ERBB2 promote act differently in breast and in ovary or colon cancer cells we have analysed." (PMID 12942124, 2003). "In addition, PAR4 agonists can induce calcium influx and promote the proliferation of colon cancer cells through ErbB2 transcription activation and Src kinase pathway." (PMID 34844621, 2021). "Human epidermal growth factor receptor 2 (HER2), alias Neu or ErbB2, is an important oncogene that has an essential function in cell proliferation and dedifferentiation and has also been extensively studied in breast, gastric, and colon cancer." (PMID 35265100, 2021). "For instance, a patient with colon cancer metastatic to the lungs and liver received Her2/ERBB2-specific CAR T cells and within 15 minutes after cell infusion the patient experienced respiratory distress and displayed a dramatic pulmonary infiltrate on a chest X-ray." (PMID 31137488, 2019). "Anticancer activity of tephrosin may be implemented through the induction of epidermal growth factor receptor (EGFR) and ErbB2 internalization and degradation of colon cancer cells as well as autophagic cell death." (PMID 31814840, 2019). "In addition, it has been described that flavonoids act as antioxidants and decreases the expression of ErbB2 and ErbB3 proteins in HT-29 human colon cancer." (PMID 30402124, 2018). "Therefore, the HRG/ErbB2/ErbB3 pathway is an important regulator of aberrant growth in colon cancer." (PMID 23739740, 2013). "Additionally, the level of phosphorylated transmembrane tyrosine kinases (e.g., ERBB2) and its interactions with other signalling factors in colon cancer cell lines may depend on endogenous HA and CD44 interaction." (PMID 37445716, 2023). "Indeed, IGF2BP2 can promote the expression of ErbB2 to repress colon cancer cells apoptosis." (PMID 35915142, 2022). "ErbB2 might stimulate the proliferation of colon cancer cells by upregulating COX2." (PMID 12942124, 2003). "For instance, a colon cancer patient with metastatic lesions in their lungs and liver was injected intravenously with 1 × 1010 CAR-T cells expressing receptor for ERBB2 (an antigen over-expressed on many solid cancers including colon cancer)." (PMID 28536354, 2017). "Structural variations were relatively infrequently to find three cases of CDKN2A, ERBB2 and EGFR amplification and single one RET-NCOA fusion in a young patient with sporadic, left colon cancer (MSI-S)." (PMID 26909603, 2016). "We analyzed the effects of exogenous heregulin on ErbB2, ErbB3 and ErbB4 phosphorylation in Caco-2, DLD-1, and HCT 116 colon cancer cell lines by western blot analysis." (PMID 25416285, 2014).
colon carcinoma (continued). "Contrary to resistance against EGFR and ERBB2 targeting, the genetic inhibition of ERBB3 results in anti-tumorigenic in HCT116 colon cancer cells harboring constitutively active KRAS and PIK3CA mutations." (PMID 24970817, 2014). "Both studies applied the combined treatment for inhibiting COX-2 and ERBB2, and COX-2 and EGFR to exert the anti-angiogeneic effect on colon cancer cell lines and xenograft models." (PMID 23967306, 2013). "The EGFR cascade was up-regulated in colonic tumors and ginseng significantly reduced EGFR and ErbB2 activation and Cox-2 expression." (PMID 22070864, 2011). "Moreover, a recent study in a model of colitis-associated colon cancer showed that ginseng reduced levels of phospho-active EGFR and phospho-active ErbB2 as well as ERK, a down stream effector of EGFR, indicating ginseng could suppress EGFR signals in colonic tumorigenesis." (PMID 22070864, 2011). "Among the upstream regulators (TFs, kinases, and MMTRs) of the DEGs, the expression of STAT3, RPS6KA5, IKBKE, ERBB2, MTOR, and NFKB1 had a positive correlation with OS in colon cancer, while the expression of CDK1, CDK5, and BRD2 had a negative correlation with OS in colon cancer." (PMID 31186640, 2019). "However, all of the normal colon samples and 27 (64%) colon tumors expressed detectable EPOR mRNA and all samples expressed detectable ERBB2." (PMID 21318160, 2010).
lung adenocarcinoma (241 papers, 1993 to 2026). A carcinoma that arises from the lung and is characterized by the presence of malignant glandular epithelial cells. "We present a 54-year-old female with stage IIIB (T1cN3M0) ERBB2 exon 20-mutated lung adenocarcinoma (PD-L1 50%) and supraclavicular metastasis." (PMID 40494858, 2025). "The ERBB2 (HER2) mutation in lung adenocarcinoma is a relatively uncommon alteration that is associated with aggressive tumor behavior, poor prognosis, and resistance to standard chemotherapy." (PMID 39823974, 2025). "EGFR, KRAS, and STK11 genes are known to be mutated in lung adenocarcinoma with a high frequency as well as ERBB2 with a lower frequency." (PMID 36499466, 2022). "Another phase II trial study evaluated 60 advanced (IIIB–IV) lung adenocarcinoma patients harboring ERBB2 mutations and previously treated with platinum‐based chemotherapy." (PMID 36251951, 2022). "The Cancer Genome Atlas (TCGA) reported a frequency of 2.6% (n = 6/230) for ERBB2‐mutated patients in lung adenocarcinomas." (PMID 36251951, 2022). "We present the case of an Asian woman diagnosed with stage IV lung adenocarcinoma harboring an ERBB2 mutation." (PMID 35677433, 2022). "The ERBB2 (HER2—human epidermal growth factor receptor 2) gene mutation encoding a receptor from the EGFR family occurs in 3% of lung adenocarcinomas." (PMID 34572931, 2021). "A subsequently larger survey of 8551 lung adenocarcinoma patients from a US‐based genomic profiling database revealed that ERBB2 TMD mutations are very rare at a frequency of 0.18%." (PMID 32478891, 2020). "Lung adenocarcinomas bearing ERBB2/3 alterations, ROS mutations and KEAP1 inactivation are also susceptible of targeting therapies." (PMID 30060526, 2018). "EGFR-mutated lung adenocarcinomas and ErbB2-positive breast and other cancers (such as gastric and lung) are critically dependent on the constitutive activity of these pathways and therapeutic targeting leads to significant clinical benefits." (PMID 29861842, 2018). "In this study, patients were initially diagnosed with lung adenocarcinoma harboring exon 20 ERBB2 mutations and had progressed under various antineoplastic regimes." (PMID 23630663, 2013). "Over-expression of erbB-2 is associated with shortened survival of patients with lung adenocarcinomas." (PMID 9569041, 1998). "Biopsy confirmed T4N0M1 lung adenocarcinoma harboring the "ERBB2 p.Y772_A775dup" mutation." (PMID 41836249, 2026). "We retrieved cases of lung adenocarcinoma with next-generation sequencing proven ERBB2 point mutations (n=8) or amplifications (n=11) and assessed the concordance of commercially available ERBB2 (HER2) immunohistochemical antibodies with the next-generation sequencing result." (PMID 37363568, 2023). "In the human lung adenocarcinoma epithelial Calu-3 cell line, it was shown that treatment with the ErbB2-targeting antibody trastuzumab was associated with increased cellular ROS production, glutathione depletion, and decreased superoxide dismutase and catalase activities." (PMID 35372019, 2022). "In particular, the small molecule EGFR TKI inhibitors, erlotinib and gefitinib show dramatic activity in EGFR-mutated lung adenocarcinomas and the anti-ErbB2 antibody, trastuzumab and the dual EGFR/ErbB2 inhibitor, lapatinib have proven benefits in ErbB2-amplified malignancies." (PMID 29861842, 2018). "Mutations that could be genuine but would require further investigation in a larger patient cohort are AKT1, FGFR1 and ERBB2, each occurring in 1/8 of the clinical samples and are reported as low frequency occurring mutations in lung adenocarcinoma by the COSMIC database." (PMID 23922754, 2013). "We report a case of a 61-year-old woman with stage IVB lung adenocarcinoma harboring an ERBB2 exon 20 insertion (p.Y772_A775dup) and a concurrent EGFR mutation, who was treated with first-line pyrotinib monotherapy." (PMID 41426315, 2025).